BUB1 (BUB1 mitotic checkpoint serine/threonine kinase)
Diseases named in the same sentence as BUB1 in open-access papers (continued):
Sharing a sentence is not in itself a finding about the gene and the disease.
breast carcinoma (continued). "Similar effects of Bub1 have been reported for breast cancer and Hela cells." (PMID 36237324, 2022). "It has been reported that depleting BUB1 could reduce cancer stem cell potential in a breast cancer cell line, resulting in inhibiting the formation of xenografts in mice." (PMID 35859724, 2022). "In brief, the analytical data suggest that SOX11, PLK1, and BUB1 may be involved in tumorigenesis to improve OS of patients with Basal-subtype breast cancer." (PMID 33644115, 2021). "Moreover, in vitro studies in breast cancer cell lines demonstrated that BUB1, like other mitotic regulators such as AurA and Plk1, is involved in the maintenance of CSC and represents a target for developing anti-CSC therapies." (PMID 34064009, 2021). "This may be due to the different roles of BUB1 in Basal-subtype and all breast cancer, which suggest a specific therapeutic target for Basal-subtype breast cancer." (PMID 33644115, 2021). "Additionally, BUB1 and BIRC5 have been linked to stemness, where depletion of BUB1 reduced cancer stem cell potential in MDA-MB-231 and MCF-7 breast cancer cell lines and BIRC5 is commonly expressed in embryonic tissues and cancer but not in adult tissues." (PMID 32457901, 2020). "The knockdown of BUB1 in the MDA-MB-231 breast cancer cell line reduced the CSC potential." (PMID 32121037, 2020). "Interestingly, a majority of Survivin interacting molecules that were found to be significantly regulated by Pirfenidone are also associated with the mitotic spindle (MAD2L1, BUB1, BUB1B, BUB3, CDC20) and were shown to be increased in human breast cancer." (PMID 32039023, 2019). "Overexpression of BUB1 was reported in non-small cell lung cancer and breast cancer." (PMID 28562334, 2017). "Bub1 expression is correlated with a poor clinical prognosis in patients with breast cancer." (PMID 26522589, 2015). "Our investigation suggests that MAD2L1 and BUB1 may play important roles in breast cancer progression, and measuring the expression of these genes may assist the prediction of breast cancer prognosis." (PMID 26287798, 2015). "Collectively, all of these observations suggest that MAD2L1 and BUB1, two genes present in multiple gene expression signatures for breast cancer prognosis, may be important molecules influencing tumor cell activity and patient survival." (PMID 26287798, 2015). "In addition, the upregulation of BUB1 protein is used as a marker, as it is upregulated in ~80% of breast cancers in paraffin-embedded tissues." (PMID 25385471, 2015). "Taken together, these results suggest that low MAD2L1 or BUB1 expression may inhibit breast cancer cell proliferation, invasion, and migration." (PMID 26287798, 2015). "Ninety genes belonging to the GO category of 'apoptosis', including members of the BAG family (BAG1, BAG2, BAG3), as well as members of the breast cancer 'proliferation signatures' (BUB1, PLK1, CCNE1, CCND1 and CCNB1) were also identified as up-regulated in our DTET." (PMID 17014703, 2006). "In addition, our results also show that FOXM1 is specifically upregulated in Basal-subtype, and whether BUB1 depends on FOXM1 to play roles requires further exploration in Basal-subtype breast cancer." (PMID 33644115, 2021). "Moreover, whether BUB1 has a tumor suppressive activity remains uncertain in Basal-subtype breast cancer, and the mechanism of BUB1 also remains to be further explored." (PMID 33644115, 2021). "Budding uninhibited by benzimidazoles 1 (BUB1) is a mitotic checkpoint serine/threonine kinase that has been reported as an oncogene or tumor suppressor gene in various types of cancer, including breast cancer, pancreatic ductal adenocarcinoma, prostate and gastric cancers." (PMID 32269624, 2020). "Here, we demonstrate that BUB1-specific inhibitor BAY1816032 radiosensitized TNBC models, a subtype of breast cancer known to have limited treatment options with poorest prognosis." (PMID 38863037, 2024).
breast carcinoma (continued). "Taken together, our data demonstrate that BUB1 is overexpressed in breast cancer including TNBC and BUB1 ablation leads to radiosensitization through regulating DNAPKcs phosphorylation and chromatin localization of key NHEJ factors." (PMID 38863037, 2024). "We identified several DEGs involved in the cell cycle, including CDK1, CHEK1, CDC25C, BUB1, CDC20, and TTK, which not only are related to breast cancer patient survival but also have existing targeted drugs." (PMID 38166892, 2024). "The five potential prognostic biomarkers, i.e., Aurora Kinase A (AURKA), BUB1 Mitotic checkpoint serine/threonine kinase B (BUB1B), Cyclin A2 (CCNA2), Cyclin B2 (CCNB2), and PDZ binding kinase (PBK) were upregulated in breast cancer." (PMID 36980449, 2023). "While BUB1, KRT5, and MYCN were overexpressed in young women with breast cancer, CXCL12 showed a decreased expression." (PMID 36685821, 2022). "This analysis indicates that the mRNA levels of multiple mitotic regulators, including TTK, Nek2, PLK1, Cyclin B1, BUB1, Aurora kinases A and B, and NDC80 (also known as HEC1) are elevated in breast cancers in NHB women." (PMID 36494865, 2022). "In the selected key specific DEGs for Basal-subtype breast cancer, the altered expression of SOX11, PLK1, BUB1, OGN, COL4A6, AGTR1, and ADRB2 were significantly correlated with the prognostic survival of the patients." (PMID 33644115, 2021). "Among patients with primary breast cancer, higher expression of MAD2L1 and BUB1 existed in patients with ER-, PR-, and high-grade tumors compared to those with ER +, PR+, and low-grade tumors." (PMID 31777591, 2019). "These genes include AURKB, BUB1, CHEK1, FOXM1, KIFC1, and TTK7, five of which, BUB1, CHEK1, FOXM1, KIFC1, and TTK, we have also identified and have functionally validated to have a selective requirement for cell growth in breast cancer cell models." (PMID 29535384, 2018). "The expression of IAK-1/Aurora A, Bub1, and BubR1 were upregulated in the HMEC spheres grown in OPG rich breast cancer cell conditioned media and recombinant human OPG." (PMID 26608463, 2015). "Restoration of miR-10b* expression by using mimic 10b* reduces PLK1, BUB1 and CCNA2 protein expression in diverse breast cancer cell lines." (PMID 23125021, 2012). "Here, we document that down-regulation of miR-10b* correlates with aberrant expression of PLK1, BUB1 and CCNA2 proteins in breast cancer specimens when compared to their matched peritumoural samples." (PMID 23125021, 2012). "In vitro investigations into adenocarcinoma of the lung and breast cancer support the notion that BAY 1816032, which was previously thought to be a newly discovered inhibitor of BUB1 catalytic activity, may have therapeutic potential for the treatment of OS." (PMID 37439040, 2023). "Although the role of other hub genes in breast cancer has not been specifically reported, studies have shown that they play an essential role in other cancers, such as BUB1 promotes proliferation by activating SMAD2 phosphorylation." (PMID 35456460, 2022). "SOX11, PLK1, BUB1, OGN, COL4A6, AGTR1, and ADRB2 may be involved in the recurrence of Basal-subtype breast cancer, and to some extent the PLK1, BUB1, OGN, COL4A6, AGTR1, and ADRB2 can be used as the specific prognostic markers for Basal-subtype breast cancer." (PMID 33644115, 2021). "However, high expression of BUB1 was associated with good prognosis (RFS and OS) in Basal-subtype breast cancer, while low expression of BUB1 predicted high RFS and OS (p < 0.05) in all breast cancer." (PMID 33644115, 2021). "In breast cancer cells, the BUB1 knockdown does not affect short-term cell growth but does impair clonogenic potency." (PMID 32781708, 2020). "Interestingly, the analysis of breast cancer datasets revealed that the expression of PICH correlates with that of mitosis-related genes, such as KIF4A, CEP55, MKI67, MELK, BUB1, CENPA, and AURKB." (PMID 31160555, 2019).
breast carcinoma (continued). "To determine factors that may induce aneuploidy, we tested the basal levels of IAK-1/Aurora A, Bub1, BubR1 and Mps1 aneuploidy kinases in HMEC and breast cancer spheres." (PMID 26608463, 2015). "The identified DEGs, which were involved in cell cycle, including CDC20, BUB1, GLIPR1, MCM2, and CCNB1, could have a crucial function in the development of breast cancer, and may become potential targets or prognostic markers for breast cancer." (PMID 25385471, 2015). "Since Bub1 also has GLEBS domain similar to that of BubR1, it may be interesting to investigate whether GLEBS domain of Bub1 is required to maintain breast cancer stem cells." (PMID 26522589, 2015). "Additionally, overexpression of BUB3, BUB1 and BUBR1 proteins has been reported in gastric cancer, clear cell kidney carcinomas and breast cancer." (PMID 24743044, 2014). "Interestingly, the analysis of gene expression databases of different cohorts of breast cancer patients reveals that those expressing high levels of PLK1, BUB1 or CCNA2 exhibit lower disease-free survival when compared to those expressing low levels." (PMID 23125021, 2012). "Moreover, it has been shown that BUB1 inhibited autophagy in breast cancer cell line MCF-7 but not in immortalized MCF-10A breast epithelial cells." (PMID 28858266, 2017). "Our analysis of MAD2L1 and BUB1 in two datasets (GSE37751 and GSE29044) also demonstrated higher expression in breast cancer than in adjacent non-tumor tissues." (PMID 26287798, 2015). "Interestingly BUB1 inhibited autophagy in breast cancer cell line MCF-7 rather than immortalized MCF-10A breast epithelial cells, which indicated the anti-cancer potential of BUB1 modulation." (PMID 28858266, 2017). "Kinases BUB1, CHEK1, IRAK1, TTK, RYK, and VRK2, identified in this study, for example, have been reported to be highly overexpressed in ER-negative breast tumors and were critical for the growth of either ER-negative only or both ER-positive and -negative breast cancer cells." (PMID 22309939, 2012).
gastric cancer (24 papers, 2004 to 2025). A primary or metastatic malignant neoplasm involving the stomach. "Mitotic spindle checkpoint gene BUB1 is linked with proliferation of gastric cancer cells, but this gene might be responsible for proliferation of pituitary prolactinoma cells." (PMID 33709028, 2021). "Moreover, Bub1 and Bub1b expression levels are drastically upregulated in gastric cancer associated with tumor cell proliferation." (PMID 26009897, 2015). "High expression of BUB1 promotes the proliferation and invasion of gastric cancer cells through the Wnt/β-catenin signaling pathway, and down-regulation of BUB1 induces S-phase arrest of liver cancer cells." (PMID 39048649, 2024). "BUB1 is reportedly overexpressed in pancreatic ductal adenocarcinoma, gastric cancer, and multiple myeloma." (PMID 36979826, 2023). "BUB1 was highly expressed in gastric cancer, and the overall survival time was prolonged in gastric cancer patients with a high expression of BUB1." (PMID 35360870, 2022). "BUB1 gene levels were found to be overexpressed in the breast and gastric cancers, as well as in lymphomas." (PMID 34884561, 2021). "Univariate and multivariate analyses confirmed BUB1 to be an independent prognostic marker in gastric cancer (p = 0.021)." (PMID 29100315, 2017). "High expression of BUB1 was observed in a variety of human malignancies including gastric cancer, colorectal cancer, and lymphomas." (PMID 26287798, 2015). "Several studies have found high Bub1 levels in subsets of breast and gastric cancers, and lymphomas." (PMID 23738901, 2013). "Previous studies of gastric cancers have found that genes such as BUB1, eRF3/GSPT1, and hCG-1 were correlated with histological type." (PMID 19337254, 2009). "Moreover, high expression of BUB1 in colon, pancreatic, lung, gastric cancer, and other solid tumors was reported previously." (PMID 40723917, 2025). "Additionally, the high BUB1 expression subtype predicted shorter survival than the low expression subtype, consistent with the study of ovarian cancer, gastric cancer, and pancreatic ductal adenocarcinoma." (PMID 35859724, 2022). "Additionally, previous studies showed a downregulation of the BUB1 gene in gastric cancer and in CRC." (PMID 33672900, 2021). "However, BUB1 and MAD2 mutations are relatively rare, and gastric cancers frequently exhibit DNA aneuploidy." (PMID 15138487, 2004). "Indeed, downregulation of Bub1 expression has been detected in a subset of acute myeloid leukemia, whereas upregulation of Bub1 levels has been reported in lymphomas, breast and gastric cancers." (PMID 26009897, 2015).
hepatocellular carcinoma (21 papers, 2019 to 2026). A malignant tumor that arises from hepatocytes. "J Cell Mol Med 22, 3434-3441.doi: 10.1111/jcmm.13620 2 Xu B, Xu T, Liu H, Min Q, Wang S and Song Q (2017) MiR-490-5p Suppresses Cell Proliferation and Invasion by Targeting BUB1 in Hepatocellular Carcinoma Cells." (PMID 37219053, 2023). "DUXAP8 serves as a sponge of MiR-490-5p to promote the expression of BUB1 in hepatocellular carcinoma." (PMID 36787437, 2023). "For example, BUB1 can enhance the proliferation of hepatocellular carcinoma cells by activating the phosphorylation of SMAD2, and BUB1B promotes liver cancer progression by activating the mechanistic target of rapamycin complex 1 (mTORC1) signaling pathway." (PMID 35493295, 2022). "Inhibition of BUB1 in hepatocellular carcinoma cells can prevent tumor proliferation and increase cell apoptosis by regulating the TGF-β/Smad signaling pathway." (PMID 34064009, 2021). "BUB1 was found as a prognostic factor for hepatocellular carcinoma." (PMID 37938151, 2023). "However, it was verified that the high expression of BUB1 was correlated with poor prognosis in hepatocellular carcinoma (HCC)." (PMID 35360870, 2022). "BUB1 may promote proliferation of hepatocellular carcinoma cells by activating phosphorylation of SMAD2." (PMID 36479313, 2022). "Nevertheless, UDCA inhibited the expression of cell cycle-related genes and the repression effect was enhanced with a time increase (PLK1, UBE2C, BUB1, CDC20, BIRC5, p <0.001) in hepatoma cell lines SNU387." (PMID 38255993, 2024). "Besides, as Xu and other researchers proposed, miR-490-5p targets BUB1 gene, thereby hampering cell proliferation, migration and invasion of hepatocellular carcinoma (HCC)." (PMID 34594374, 2021). "Furthermore, CCNB2, MAD2L1, BUB1, and NCAPG are significantly upregulated in hepatocellular carcinoma (HCC) tissues and are implicated in the growth and metastasis of HCC cells." (PMID 32265985, 2020). "Adopting a series of bioinformatics analysis methods, the current study identified 763 DEGs and seven hub genes (CDC20, CDK1, MAD2L1, BUB1, BUB1B, CCNB1, and CCNA2) that may be involved in hepatocellular carcinoma tumorigenesis and progression." (PMID 33767726, 2021). "On the other hand, studies have shown that overexpression of BUB1/BUB1B is related to progression and recurrence of various tumors including glioblastoma, pancreatic ductal adenocarcinoma, prostate cancer, gastric adenocarcinoma, and hepatocellular carcinoma." (PMID 33872216, 2021). "The results showed that AC099850.3 could promote the migration and proliferation of hepatocellular carcinoma cells in vitro, and RT-PCR experiments found that AC099850.3 could promote the expression of the cell cycle molecules BUB1, CDK1, PLK1, and TTK." (PMID 34123835, 2021). "Not surprisingly, among them, CDC20, CCNA2, and BUB1 are all associated with APC-related processes, which may be key nodes in the prognosis and occurrence of hepatocellular carcinoma." (PMID 36479313, 2022).
ovarian carcinoma (19 papers, 2009 to 2024). A malignant neoplasm originating from the surface ovarian epithelium. "Similarly, strategies to target BUB1 are under preclinical evaluation as this kinase has been described as associated with detrimental prognosis in breast and ovarian cancer." (PMID 29330624, 2018). "Reported four genes (BUB1B, BUB1, TTK and CCNB1) that were up-regulated DEGs in ovarian cancer associated with poor prognosis using integrated bioinformatical methods." (PMID 39048649, 2024). "BUB1 and BUB1B genes were identified as significant hub differentially expressed genes in epithelial ovarian cancer associated with a poor prognosis." (PMID 39048649, 2024). "In a bioinformatics study, BUB1 was reported to be overexpressed in ovarian cancer compared to normal ovarian tissue." (PMID 34820170, 2021). "BUB1 is an independent prognostic indicator for ovarian cancer and was found depleted in paclitaxel resistant human ovarian cancer cells." (PMID 34266348, 2021). "Down-regulation of BUB1 expression levels suppressed ovarian cancer progression." (PMID 35719392, 2022). "BUB1 has been found to be upregulated and to promote cancer proliferation and metastasis in various types of cancers, including pancreatic ductal adenocarcinoma and ovarian cancer." (PMID 32849765, 2020). "Here, we report that the overexpressed genes IRAK1, CHEK1 and BUB1 may play an important role in ovarian cancer." (PMID 23383610, 2013). "This study suggests that of the 17 shortlisted genes flagged as significant, the overexpressed genes IRAK1, CHEK1 and BUB1 may play an important role in ovarian cancer." (PMID 23383610, 2013). "BUB1 overexpression weakens KIF4A knockdown-mediated effects on cell viability, colony formation, migration, and apoptosis in ovarian cancer." (PMID 36787437, 2023). "Our further qRT-PCR showed that seven hub genes (BUB1, KIF2C, NUP43, NDC80, NUF2, CCNB2 and CENPN) were differentially expressed in platinum-resistant ovarian cancer cells." (PMID 34820170, 2021). "Our study revealed gene depletion across a number of molecular components involved in the spindle assembly checkpoint and mitotic regulation, including BUB1, CCNB1, CENPE and CENPF in paclitaxel resistant ovarian cancer cell lines." (PMID 29618387, 2018). "A recent study on ovarian cancer supports our observation that the cell cycle proteins, CHEK1 and BUB1, are over-expressed and are important to the tumor condition, lending support to our observation." (PMID 23383610, 2013). "Since Bub1 inhibitors are under evaluation for their anti-cancer potential, for this assay, we compared three different human cell lines: the ovarian cancer cell lines OVCAR-3 and Kuramochi, and the non-transformed cell line RPE1 for comparison." (PMID 34925867, 2021). "For instance, four genes (BUB1B, BUB1, TTK, and CCNB1) that are pronouncedly upregulated in ovarian cancer and indicate dismal prognosis were disclosed through bioinformatic methods, and they can be used as potential therapeutic targets for patients with ovarian cancer." (PMID 34434217, 2021). "While little workhas been done on BUB1 itself, other members of the spindle assembly checkpoint havebeen investigated in the context of ovarian cancer including BUBR1, which is anindependent prognostic indicator for ovarian cancer." (PMID 21423607, 2011). "Furthermore, despite the incidence of CIN in ovarian cancers, the status of SAC proteins such as Bub1, Mad2, Mad1, and BubR1 had not been satisfactorily addressed." (PMID 19603021, 2009).